LINC00659 (long independently transcribed non-coding RNA 659)
Gene: Long non-coding RNA gene on chromosome 20 (62,772,665 to 62,777,067, reverse strand). Ensembl gene ENSG00000228705.
Diseases named in the same sentence as LINC00659 in open-access papers:
LINC00659 is named in the same sentence as 10 diseases in open-access papers, as found by Europe PMC text mining. Sharing a sentence is not in itself a finding about the gene and the disease. The quoted sentences say what the papers report.
colorectal cancer (6 papers, 2018 to 2023). A primary or metastatic malignant neoplasm that affects the colon or rectum. "LINC00659 is highly expressed in CAFs compared to normal fibroblasts and is transferred from CAFs to colorectal cancer cells via exosomes." (PMID 38933287, 2023). "For all we know, LINC00659 has been reported to function as oncogenes in a variety of cancers, such as gastric cancer and colorectal cancer." (PMID 37234237, 2023). "Further possible events that favoured transformation are the gain of the oncogenes GNAS (a PDAC driver gene), LINC00659 (an oncogene in colorectal cancer), and ZNF217 (an oncogene in many solid tumours, including PDAC)." (PMID 36289850, 2022). "Recently, LINC00659 was demonstrated to be distinctly upregulated in colorectal cancer, which was in line with our findings." (PMID 35957833, 2022). "Our aim was to clarify the role of LINC00659 encapsulated in CAFs-derived exosomes (CAFs-exo) in colorectal cancer (CRC)." (PMID 33407563, 2021). "LINC00659 interacts with miR-342-3p to promote ANXA2 expression and induces propagation, invasion, migration, and EMT of colorectal cancer cells." (PMID 38933287, 2023).
colon cancer (3 papers, 2018 to 2023). "We first reported that the expression levels of Linc00659 were significantly increased in colon cancer and that Linc00659 loss suppressed colon cancer cell growth by impairing cell cycle progression." (PMID 29523145, 2018). "Functionally, it was observed that knockdown of LINC00659 suppressed colon cancer cell growth and accelerate cell apoptosis via modulating PI3K-AKT signaling, suggesting that LINC00659 served as a tumor promoter in colon cancer." (PMID 35957833, 2022). "Using bioinformatics approach to illustrate putative biological function of Linc00659 in colon cancer." (PMID 29523145, 2018). "Linc00659 is a novel oncogenic lncRNA involved in colon cancer cell growth by modulating the cell cycle." (PMID 29523145, 2018). "A total of 1218 protein-coding genes were coexpressed with Linc00659 in colon cancer (r > 0.7 or <− 0.7)." (PMID 29523145, 2018). "Among them, the expression levels of Linc00659 were significantly increased in colon cancer, and high expression levels were correlated with poor survival in patients with CRC." (PMID 29523145, 2018). "An analysis of the Gene Expression Omnibus database showed that the expression levels of Linc00659 were increased in drug-resistant breast and colon cancer cells." (PMID 29523145, 2018). "Overall, the expression levels of Linc00659 conferred drug sensitivity in colon cancer by inducing apoptosis." (PMID 29523145, 2018). "The expression levels of Linc00659 significantly increased in colon cancer compared with normal mucosa." (PMID 29523145, 2018). "We further explored the biological role of Linc00659 in colon cancer tumorigenesis by identifying coexpression gene networks." (PMID 29523145, 2018). "Compared with adjacent normal mucosa, the expression levels of Linc00659 were clearly overexpressed in eight colon cancer cell lines by more than 20-fold." (PMID 29523145, 2018). "We analyzed the subcellular localization of Linc00659, revealing that Linc00659 expression occurred both in the nucleus and cytoplasm in most colon cancer cells." (PMID 29523145, 2018). "For example, knockdown of LINC00659 could significantly inhibit colon cancer growth by inducing apoptosis." (PMID 36705418, 2023). "Thus, our findings indicated that higher levels of LINC00659 displayed tumor-promotive roles in GC progress, which was consistent with its function in colon cancer." (PMID 35957833, 2022). "In our study, we demonstrated that Linc00659 knockdown could accelerate cell apoptosis in colon cancer cells following oxaliplatin treatment." (PMID 29523145, 2018). "Using an experimental approach, we further confirmed that Linc00659 knockdown could significantly suppress colon cancer growth by impairing cell cycle progression and inducing cell apoptosis." (PMID 29523145, 2018). "Linc00659 expression knockdown could significantly suppress colon cancer cell growth by impairing cell cycle progression." (PMID 29523145, 2018). "According to its location, Linc00659 might regulate colon cancer cell growth by binding with microRNA sponge, regulate transcription factors, or modulate epigenetic modification to prevent tumor suppressor gene expression." (PMID 29523145, 2018). "In addition, our results showed that Linc00659 expression knockdown could accelerate cell apoptosis in colon cancer cells treated with chemotherapy drugs." (PMID 29523145, 2018). "Notably, we also found that Linc00659 expression had a highly positive correlation with cell cycle-related gene expression in colon cancer, implying that Linc00659 might have an oncogenic role in colon cancer cell growth by accelerating cell cycle progression." (PMID 29523145, 2018). "Our results revealed that Linc00659 could regulate colon cancer growth." (PMID 29523145, 2018).
colon cancer (continued). "Our results indicated that the expression levels of Linc00659 and MNX1-AS1 were significantly increased, whereas those of Loc339524 and Linc00657 were significantly decreased in colon cancer, which were consistent with our microarray results." (PMID 29523145, 2018). "Meanwhile, our results also demonstrated that silencing of Linc00659 expression leads to cell growth inhibition and induced apoptosis, possibly by suppressing PI3K-AKT signaling in colon cancer." (PMID 29523145, 2018). "Taken together, our results demonstrate a putative mechanism of Linc00659 knockdown that impairs cell cycles and induces apoptosis; this may be a result of suppressing the PI3K-AKT-GSK3B axis in colon cancer." (PMID 29523145, 2018). "Furthermore, high expression levels of Linc00659 were significantly correlated with a short survival curve of patients with CRC, implying that Linc00659 might play an oncogenic role in colon cancer progression." (PMID 29523145, 2018).
gastric cancer (3 papers, 2020 to 2023). A primary or metastatic malignant neoplasm involving the stomach. "As a result, LINC00659 expression was increased in gastric cancer tissues, which was closely associated with tumour stage and lymph node metastasis, but was not correlated with age, gender and tissue differentiation." (PMID 33145980, 2020). "The high expression of LINC00659 can promote the proliferation, metastasis and invasion of gastric cancer, which is related to the promotion of SUZ12 transcription factor expression." (PMID 33145980, 2020). "In summary, here, we show that LINC00659 is involved in the carcinogenesis and progression of gastric cancer." (PMID 33145980, 2020). "A total of 80 patients with gastric cancer were divided into LINC00659 high expression group and low expression group (N = 40 each) according to the cut‐off value of 0.58 of LINC00659 relative expression." (PMID 33145980, 2020). "In our previous screening, LINC00659 is highly expressed in gastric cancer; however, its role in gastric cancer and its possible correlation with pathological parameters have not been revealed." (PMID 33145980, 2020). "The relative expression of LINC00659 in gastric cancer tissues was (0.53 ± 0.10), which was significantly higher than that in adjacent tissues (0.28 ± 0.08) (P < .01)." (PMID 33145980, 2020). "In this study, we first validated that the expression of LINC00659 was increased in gastric cancer tissues." (PMID 33145980, 2020). "The expression of LINC00659 was increased in gastric cancer cell lines, SGC‐7901 and BGC‐823." (PMID 33145980, 2020). "Therefore, in this study, we mainly investigate the correlation between LINC00659 and clinical and prognostic factors in patients with gastric cancer through clinical samples, and to reveal the mechanism of LINC00659 in metastasis and invasion in gastric cancer." (PMID 33145980, 2020). "Additionally, LINC00659 could regulate cell cycle and invasion of gastric cancer by promoting the expression of SUZ12." (PMID 33145980, 2020). "The expression of LINC00659 was significantly higher in gastric cancer cell lines (SGC‐7901 and BGC‐823), compared with that in normal cells (GES‐1) (P < .01)." (PMID 33145980, 2020).
leprosy (1 paper, 2021). Leprosy is a chronic infectious disease affecting primarily the skin and peripheral nervous system. "These candidate genes were then validated using PBMCs of MB and PB leprosy patients, HHCs, and ECs in a separate validation cohort, and we found that elevated expression of a 5-gene set IL-8, CCL2/MCP-1, SERP, LINC00659 and FLJ10489 could discriminate leprosy patients from ECs." (PMID 34993156, 2021).
lymph node metastasis (1 paper, 2020). "Additionally, the expression level of LINC00659 was associated with the stage and lymph node metastasis but was not correlated with age, gender or histological differentiation." (PMID 33145980, 2020).
Varicose veins (1 paper, 2023). Enlarged and tortuous veins. "LINC00659 was aberrantly expressed in the venous tissues of patients with varicose veins by GSE51260 dataset microarray analysis." (PMID 36890543, 2023).
Venous thrombosis (1 paper, 2023). Formation of a blood clot (thrombus) inside a vein, causing the obstruction of blood flow. "LINC00659 was found to be involved in varieties of diseases, including cancer and venous thrombosis." (PMID 36705418, 2023).
tumor (8 papers, 2016 to 2024). "IHC staining assays demonstrated that knocking down LINC00659/ALKBH5 decreased JAK1 expression in tumours, while overexpressing LINC00659/ALKBH5 increased the expression of JAK1." (PMID 36864711, 2023). "The tumours harvested from the LINC00659‐overexpressing group were larger and heavier than tumours from the NC group, with higher Ki‐67 protein levels." (PMID 36864711, 2023). "After LINC00659 inhibition, the protein levels of SUZ12, p21, Cyclin E, Cyclin D and CDK2 in SGC‐7901 tumour tissue were significantly higher than those of SGC‐7901‐LINC00659−/−." (PMID 33145980, 2020). "The expression of LINC00659 in tumour tissues was evaluated using RT‐qPCR." (PMID 36864711, 2023). "However, our study for the first time demonstrated the tumor-suppressor potential of LINC00659 in HCC." (PMID 37234237, 2023). "RT‐qPCR assays verified the knockdown of LINC00659 expression in mouse tumour tissues." (PMID 36864711, 2023). "Besides, bioinformatics analysis by “lnCar” algorithm using another microarray data (GSE99416) also confirmed that LINC00659 was up-regulated in GC tumor tissues." (PMID 35957833, 2022). "Data from qPCR also proved that LINC00659 was upregulation in 120 GC tumor specimens." (PMID 35957833, 2022). "In addition, they reported that Linc00659 was highly expressed in primary tumor tissues with a higher H3K4me3 signal in its promoter region, compared with normal tissues." (PMID 29523145, 2018). "Furthermore, LINC00659 was also highly expressed in GC tumor cells." (PMID 35957833, 2022). "As distinguished from other studies of LINC00659 functioning in tumor cells, our study focused on the function of LINC00659 in assisting CAFs to regulate CRC, indicating that targeting LINC00659 or blocking its transport from CAFs to CRC cells could be a possible strategy for CRC treatment." (PMID 33407563, 2021). "Therefore, from the 77 epithelial lncRNAs which were upregulated in tumor samples we prioritized 11 candidates: AC016735.1, AC123023.1, BBOX1−AS1, CASC19, LINC00659, FEZF1−AS1, LINC00460, RP11−595B24.2, RP11−796E10.1, RP5−940J5.9 and RP11−350J20.12." (PMID 38740871, 2024).
cancer (7 papers, 2018 to 2023). A tumor composed of atypical neoplastic, often pleomorphic cells that invade other tissues. "The KEGG pathway analysis using “lnCar” algorithm also indicated that LINC00659 was associated with “pathways in cancer”." (PMID 35957833, 2022). "Our previous study indicated that LINC00659 knockdown and chemotherapy drugs have a synergistic effect, resulting in drug sensitivity to accelerated apoptosis in cancer cells through the modulation of PI3K/AKT signaling." (PMID 35406629, 2022). "Functional studies reveal that LINC00659 is transferred from CAFs to the cancer cells via exosomes, where it promotes CRC cell proliferation, invasion, migration and EMT progression in vitro." (PMID 33407563, 2021). "Knockdown of Linc00659 expression significantly suppressed cancer cell proliferation and colony formation in HCT116." (PMID 29523145, 2018). "In this study, we used TCGA database to determine coexpressed protein-coding genes and demonstrate the biological function of Linc00659 involved in modulating cancer cell growth." (PMID 29523145, 2018). "Moreover, LINC00659 is abundantly expressed in CAF-derived exosomes, and LINC00659 uptake by cancer cells leads to enhanced proliferation and EMT." (PMID 35055115, 2022). "The results displayed that LINC00659 levels in CRC tissues were stronger than in adjacent cancer tissues (P< 0.05) and further analysis found that high expression of LINC00659 predicted a relatively poor prognosis while low expression of LINC00659 is associated with better prognosis (P< 0.05)." (PMID 33407563, 2021).
LINC00659 also shares sentences with these, for which no sentence is quoted: deep vein thrombosis (1 paper).